EBF1 (EBF transcription factor 1)
Description:
Key pioneer transcription factor of B-cell specification and commitment. Recognizes variations of the palindromic sequence 5'-ATTCCCNNGGGAATT-3'. Operates in a transcription factor network to activate B-cell-specific genes and repress genes associated with alternative cell fates. For instance, positively regulates many B-cell specific genes including BCR or CD40 while repressing genes that direct cells into alternative lineages, including GATA3 and TCF7 for the T-cell lineage. In addition to its role during lymphopoiesis, controls the thermogenic gene program in adipocytes during development and in response to environmental cold (By similarity). (Microbial infection) Acts as a chromatin anchor for Epstein-Barr virus EBNA2 to mediate the assembly of EBNA2 chromatin complexes in B-cells. In addition, binds to the viral LMP1 proximal promoter and promotes its expression during latency.
Synonyms: O/E-1; COE1; EBF; OLF1
Tractability: Small molecule: a structure with a bound ligand is known. PROTAC: UniProt records ubiquitination sites on it; ubiquitination databases record sites on it; its protein half-life has been measured.
Gene: Protein-coding gene on chromosome 5 (158,695,920 to 159,099,951, reverse strand). Ensembl gene ENSG00000164330.
Subcellular location: Nucleus
Subcellular location (Human Protein Atlas): Nucleoplasm; Vesicles
Pathways (Reactome):
Developmental Biology: Transcriptional regulation of white adipocyte differentiation
Sensory Perception: Expression and translocation of olfactory receptors
Gene Ontology:
Molecular function: protein binding; DNA-binding transcription factor activity, RNA polymerase II-specific; RNA polymerase II cis-regulatory region sequence-specific DNA binding; DNA binding; DNA-binding transcription activator activity, RNA polymerase II-specific; DNA-binding transcription factor activity
Biological process: regulation of transcription by RNA polymerase II; positive regulation of transcription by RNA polymerase II; regulation of DNA-templated transcription
Cellular component: chromatin; nucleus
Genetic constraint (gnomAD): Loss-of-function variants: 10 observed, 64.16 expected, observed/expected ratio (o/e) 0.16, 90% interval 0.095 to 0.26. The upper end of that interval is the gene's LOEUF score, 0.26, which puts it in group 1 of 6, group 1 being the genes least tolerant of losing a copy. Missense variants: 507 observed, 774.44 expected, observed/expected ratio (o/e) 0.65, 90% interval 0.61 to 0.7. Synonymous variants: 298 observed, 297.26 expected, observed/expected ratio (o/e) 1, 90% interval 0.91 to 1.1.
Cancer hallmarks: suppression of growth (promotes)
Homologues: Orthologues: chimpanzee EBF1 (100% identical), macaque EBF1 (100% identical), mouse Ebf1 (100% identical), rabbit EBF1 (100% identical), rat Ebf1 (100% identical), guinea pig EBF1 (99% identical), pig EBF1 (99% identical), dog EBF1 (99% identical), tropical clawed frog ebf4 (93% identical), zebrafish ebf1a (93% identical), zebrafish ebf1b (90% identical), Drosophila melanogaster kn (59% identical), and 2 more. Paralogues in human: EBF3 (89% identical), EBF2 (77% identical), EBF4 (73% identical).
Diseases named in the same sentence as EBF1 in open-access papers:
EBF1 is named in the same sentence as 112 diseases in open-access papers, as found by Europe PMC text mining. Sharing a sentence is not in itself a finding about the gene and the disease. The quoted sentences say what the papers report.
leukemia (22 papers, 2009 to 2025). A malignant (clonal) hematologic disorder, involving hematopoietic stem cells and characterized by the presence of primitive or atypical myeloid or lymphoid cells in the bone marrow and the blood. "Nevertheless, when crossed to additional leukemia predisposing backgrounds (e.g. Ebf1 or Ikzf1, Stat5b or BCR-ABLp190) or challenged through external stressors (e.g. infection exposure or antibiotics) Pax5± mice develop an aggressive BCP-ALL that closely resembles the human disease." (PMID 40394211, 2025). "Concerning SOX4 and EBF1, it is known that both genes enable the survival signaling of leukemia cells." (PMID 38339034, 2024). "EBF1 is a tumor suppressor in breast cancer, leukemia, and colorectal cancer and inhibits gastric cancer progression by repressing the telomerase catalytic subunit." (PMID 39236081, 2024). "Among the transcriptomic subtypes, EBF1 alterations were restricted to Early-Pro leukemias (n = 8/23, 35%; P = 0.0018, Fisher’s exact test is used throughout this section)." (PMID 37337105, 2023). "C3 leukemias also showed marked upregulation of B-cell transcription factors, EBF1 and PAX5, and B-cell receptor signaling genes." (PMID 37337105, 2023). "For instance, Stat5b-CA x Ebf1+/− and Stat5b x Pax5+/− transgenic mice develop rapid onset leukemia with complete penetrance whereas leukemogenesis is somewhat less efficient when crossing Stat5b-CA with Rag2−/− or μMT−/− mice." (PMID 34736527, 2021). "As a transcript factor, EBF1 over-expression increases DNA damage by directly targeting RAD51 in leukemia, while EBF1 knockdown promotes cell proliferation and migration by increasing CD133, Oct3/4, and TFF1 expression in CCA." (PMID 32676457, 2020). "This has been verified in mouse models where heterozygote deletion of Pax5 in combination with expression of constitutively active STAT5 or partial inactivation of the Ebf1 gene largely increase leukemia formation." (PMID 31381561, 2019). "Approximately half of Ebf1+/–Bcl-xLTg mice develop aggressive oligoclonal leukemia as they age, which engrafts in congenic wild-type recipients without prior conditioning." (PMID 28692033, 2017). "Decreased expression of Pax5 and Ebf1 also occurred in the post-CD19 CAR leukaemia from patient ALL_H0140 demonstrating lineage." (PMID 27460500, 2016). "Many deletions (i.e., Cdkn2a, Ebf1, Pax5, Ikzf1) involved B-cell development genes and tumor suppressor genes, recapitulating deletions occurring in human leukemia." (PMID 23487523, 2012). "Here, beyond demonstrating that EBF1 is an Ikaros target, we also provided strong lines of evidence that Ikaros deletion directly reduces activation of EBF1 in leukemia cells contributing to an extensive block of B-cell differentiation." (PMID 22848414, 2012). "While early studies generally identified EBF1 as a tumor suppressor in leukemia, some research has indicated that it may also exhibit oncogenic potential in certain hematologic malignancies, suggesting that its function is highly context-dependent." (PMID 40508012, 2025). "Loss of EBF1 contributes to the development of B-ALL and over-expression of EBF1 increases DNA damage in a dose-dependent manner, indicating a tumor suppressor role for EBF1 in leukemia." (PMID 32676457, 2020). "Moreover, EBF1 regulates DNA repair in a dose-dependent manner by direct effects on RAD51, and combined loss of EBF1 and Pax5 predisposes patients to leukemia development." (PMID 32676457, 2020). "Genes that have been reported as abnormally methylated in leukemia, including CPEB1, BLK, FLT3, PAX5, EBF1, HDACs, IKZF1, RB, etc., were also detected in this study." (PMID 41226303, 2025).
leukemia (continued). "As expected, several previously reported genes with abnormal methylation in leukemias such as CPEB1, BLK, FLT3, ZCCHC7, EBF1, HDACs, IKZF1, RB1, CDK6, DOCK5, DPP10, MUC4, JAKs, KIT, KRAS, LINC01013, MAD1L1, NOTCH1, and STATs, among others, were also detected." (PMID 41226303, 2025). "Two Early-Pro cases, Ph28-D and Ph50-D, harbored concurrent deletions of EBF1, PAX5, RUNX1 and CDKN2A/B and clustered between Early-Pro and Late-Pro leukemias in PCA." (PMID 37337105, 2023). "Rather, CD19-expressing B-ALL cells are continuously being deleted under this pressure, until leukaemia either downregulates CD19 (in two of our samples) or reprograms via downregulation of PAX5 and EBF1 to drive a CD19 CAR-resistant relapse." (PMID 27460500, 2016). "Similarly, we showed that PAX5, EBF1, CD72 and TCL1A are tightly correlated in the capacity to distinguish lymphoblastic and myeloblastic characteristics also in the presence of MLL mutations illustrating the importance of B-cell receptor signaling pathway in this subset of leukemias." (PMID 19549311, 2009). "Strikingly, this IGH germline ALL group exhibited a high frequency of IKZF1 deletions and non-V(D)J rearrangements including CRLF2-IGH, EPOR-IGH, and EBF1-PDGFRß that can be exploited as leukemia-specific targets in clinical diagnostics of MRD." (PMID 31784504, 2019). "Ebf1 and Pax5 deletions, though not sufficient to induce leukemia of their own accord, can each induce leukemia in mice with constitutive STAT5b activation." (PMID 23487523, 2012).
breast cancer (14 papers, 2012 to 2025). A primary or metastatic malignant neoplasm involving the breast. "Decreased EBF1 expression resulting from genomic loss or somatic missense mutations were found in breast cancer (BC), pancreatic ductal adenocarcinoma (PDAC), and cholangiocarcinoma (CCA)." (PMID 32676457, 2020). "The association of SNP rs1432679 (EBF1 gene) with breast cancer appears to correlate with mammographic density phenotypes." (PMID 27863437, 2016). "EBF1 plays a direct role in breast cancer (BC) progression by modulating tumor metabolism-related pathways." (PMID 40508012, 2025). "Motif discovery identified motifs associated with three transcription factors—EBF1, ZNF770, and PATZ1—suggesting potential regulatory mechanisms influencing gene expression and breast cancer intrinsic subtypes." (PMID 39452108, 2024). "The study found that one locus (rs1432679, p=0.043) in the EBF1 gene, another one (rs10759243, p =0.012) in the KLF4-RPL36AP6 gene, and yet another (rs10822013, p =0.046) in ZNF365 gene were association with breast cancer based on χ2 tests." (PMID 27863437, 2016). "One could imagine that EBF-1 functions to differentially modulate the balance between ERα and ERβ activities in breast cancers that express both ER subtypes, resulting in diverse transcriptional and phenotypic consequences." (PMID 23951143, 2013). "EBF1 is only deregulated in lung cancer, but only in two of the ten datasets, while RUNX1 is deregulated in lung cancer and breast cancer, but its regulation varies: it is positive in some datasets and negative in others of the same type of cancer." (PMID 36101460, 2022). "Additionally, EBF1 promotes breast cancer progression through the HIF1α pathway, and inhibition of thyroid cancer progression by noncoding RNA LINC00261 can be achieved through the regulation of EBF1." (PMID 39794701, 2025).
acute lymphoblastic leukemia (11 papers, 2015 to 2025). Leukemia with an acute onset, characterized by the presence of lymphoblasts in the bone marrow and the peripheral blood. "The functional dysregulation of EBF1 expression is intricately associated with the occurrence, recurrence, and treatment resistance of B-lineage acute lymphoblastic leukemia." (PMID 40508012, 2025). "ABL-class fusions including NUP214-ABL1 and EBF1-PDGFRB occur in high risk acute lymphoblastic leukaemia (ALL) with gene expression patterns similar to BCR-ABL-positive ALL." (PMID 35650277, 2022). "Mutations in EBF1 are common in acute lymphoblastic leukemia, and heterozygosity of this gene is associated with increased DNA damage and decreased homologous recombination through decreased Rad51 expression and decreased apoptosis in mice." (PMID 34379776, 2021). "Being EBF1, together with E2A and Pax5, involved in the B-cell lineage commitment by regulating cell transcription, it has been also implicated in the development of B-cell-acute lymphoblastic leukemias (B-ALL)." (PMID 38035116, 2023). "Accumulating evidence indicates that genomic deletion of the EBF1 gene contributes to the pathogenesis, drug resistance, and relapse of B-progenitor acute lymphoblastic leukemia (ALL)." (PMID 25609158, 2015). "Pediatric B-cell precursor acute lymphoblastic leukemia (BCP-ALL) is associated with a high frequency of copy number alterations (CNAs) in IKZF1, EBF1, PAX5, CDKN2A/B, RB1, BTG1, ETV6, and/or the PAR1 region (henceforth: B-cell development genes)." (PMID 30874617, 2019). "However, in some instances of acute lymphoblastic leukemia (ALL), aberrant expression of EBF1 is frequently detected, adversely impacting the normal development and differentiation of B cells and associated with the occurrence, drug resistance, and recurrence of ALL." (PMID 40508012, 2025). "Genome‐wide studies demonstrated that 60% of all B‐cell precursor acute lymphoblastic leukemia (B‐ALL) cases carry genetic alterations in genes coding for regulators of B cell development, with the most commonly affected transcription factor genes being PAX5, EBF1, and IKZF1 (Ikaros)." (PMID 35156727, 2022).
colorectal cancer (11 papers, 2019 to 2025). A primary or metastatic malignant neoplasm that affects the colon or rectum. "EBF1 protein levels have been otherwise associated to better prognosis in colorectal cancer and cholangiocarcinoma and to a worse outcome in triple-negative breast cancer." (PMID 38035116, 2023). "The transcription factor EBF1 enhances the transcription of USP5 in colorectal cancer cells by binding to its promoter." (PMID 39761299, 2025). "Oncomine analysis of EBF1 expression in colorectal cancer (total 4 colorectal cancer cohorts)." (PMID 32676457, 2020). "Early B cell factor 1 (EBF1) has been identified as an upstream transcription factor of the potential oncogene PNO1 and is involved in the growth of colorectal cancer (CRC) cells." (PMID 32676457, 2020).
gastric cancer (8 papers, 2021 to 2025). A primary or metastatic malignant neoplasm involving the stomach. "Lastly, mutations in EBF1 are observed in some gastric cancer cells." (PMID 39871386, 2025). "We also found that most of the circRNAs among the seven different cancers are unique, except hsa_circ_0074817| EBF1, which was common between liver cancer and thyroid cancer and hsa_circ_0001821| circPVT1, which was common between head and neck cancer and gastric cancer." (PMID 34055888, 2021). "EBF1 exerts its anti-cancer effects in gastric cancer (GC) primarily by transcriptionally repressing key oncogenes." (PMID 40508012, 2025). "However, in gastric cancer cells, multiple mechanisms inhibit the normal function of EBF1." (PMID 39871386, 2025). "Of note, EBF1 was recently shown to be a tumor suppressor in gastric carcinoma and is frequently inactivated in these tumors (including the AGS gastric carcinoma cell line)." (PMID 35472072, 2022).
Obesity (7 papers, 2012 to 2025). Accumulation of substantial excess body fat. "Other hypertension-associated genes impacted by obesity included Podxl and Ebf1 upregulated in lung art ECs, Nbeal1 and Tbx3 upregulated in heart art ECs and Igfbp3 with reduced expression in heart, kidney and brain art ECs." (PMID 36400935, 2022). "We achieved replication of the EBF1 SNPxSTRESS association with obesity, however, also only in White samples." (PMID 33077726, 2020). "In prior work, we identified a novel gene-by-stress association of EBF1’s common variation (SNP rs4704963) with obesity (i.e., hip, waist) in Whites, which was further strengthened through multiple replications using our synthetic stress measure." (PMID 33077726, 2020). "Underscoring the race-specific key life-stress indicators (e.g., racism/discrimination) and also the utility of our synthetic stress, we identified the potential risk group of EBF1 and stress-induced human obesity and cardiometabolic disease." (PMID 33077726, 2020). "Dysregulated expression of EBF1 is associated with adipose hypertrophy, adipose inflammation, variation in body fat distribution and altered adipose morphology through impaired adipogenesis, which in turn has been implicated as a key factor in the development of obesity related traits." (PMID 33420178, 2021). "These factors, which include Rb, Maf, fosB, Taz, and Ebf1, have been the subjects of intense inquiry given obvious links to two human diseases of great importance, osteoporosis and obesity." (PMID 23209378, 2012). "A few key pieces of data examining the role of EBF1 in human obesity seem ostensibly inconsistent with my hypothesis that EBF1 permissively promotes a normal inflammatory response in adipocytes, perhaps even arguing against it." (PMID 33732506, 2021). "Most of those loci have been associated with childhood BMI/obesity in previous GWAS but not with birth weight, whereas one locus (EBF1) was novel to childhood obesity and one locus (LMBR1L) was novel to both birth weight and childhood BMI/obesity." (PMID 33420178, 2021). "Taken together, these data seem to directly contradict my hypothesis that EBF1 promotes normal adipose inflammation in obesity (since several studies have confirmed that EBF1 or Ebf1 expression is lower in larger—and presumably more inflammation-prone-fat cells)." (PMID 33732506, 2021). "Our findings provided additional confirmation that genetic variation in EBF1 may contribute to stress-induced human obesity, including in Blacks (P = 0.022) that mainly resulted from race-specific stress due to “racism/discrimination” (P = 0.036) and “not meeting basic needs” (P = 0.053)." (PMID 33077726, 2020).